HSF1 (heat shock transcription factor 1)
Diseases named in the same sentence as HSF1 in open-access papers (continued):
Sharing a sentence is not in itself a finding about the gene and the disease.
fibrosis (1 paper, 2017). the formation of excess fibrous connective tissue in an organ or tissue in a reparative or reactive process. "We showed for the first time that HSF1 acts as novel negative regulator of cardiac fibrosis by blocking Smad3 activation." (PMID 28091697, 2017). "In conclusion, the present study demonstrated for the first time that HSF1 acts as a novel negative regulator of cardiac fibrosis by blocking Smad3 activation." (PMID 28091697, 2017). "As stress-induced Smad3 activation and nuclear translocation play critical roles in cardiac fibrosis and remodeling, our finding of HSF1-mediated Smad3 inhibition prompted us to examine whether HSF1 directly interacted with Smad3." (PMID 28091697, 2017).
gliosarcoma (1 paper, 2013). A rare histological variant of glioblastoma (WHO grade IV) characterized by a biphasic tissue pattern with alternating areas displaying glial and mesenchymal differentiation (WHO). "GA can activate HSF1 which results in the induction of Hsp70 as previously demonstrated in certain experimental models, e.g. K562 erythroleukemic or rat 9L gliosarcoma cells." (PMID 24015183, 2013).
hearing loss (1 paper, 2021). "Our results suggest that decreased HSF1 expression may be a main cause of age-related hearing loss." (PMID 34572102, 2021).
inflammatory bowel disease (1 paper, 2018). A spectrum of small and large bowel inflammatory diseases of unknown etiology. "Further, we found known associations between KLF6, NR3C1, XBP1 and HSF1 with inflammatory bowel disease further validating our analyses." (PMID 30184180, 2018).
intrahepatic cholangiocarcinoma (1 paper, 2024). A carcinoma that arises from the intrahepatic bile duct epithelium in any site of the intrahepatic biliary tree. "To determine the role of HSF1 in human intrahepatic cholangiocarcinoma (iCCA), we assessed first its levels in this disease." (PMID 39243039, 2024).
invasive carcinoma (1 paper, 2018). A carcinoma that is not confined to the epithelium, and has spread to the surrounding stroma. "HSF1 expression was linked to high histologic grade, larger tumor size, and nodal involvement at diagnosis in invasive carcinomas." (PMID 29494616, 2018).
invasive ductal carcinoma (1 paper, 2023). "We have previously shown that nuclear expressions of DYRK2 and HSF1 correlate in TNBC and quadruple-negative breast cancer (QNBC: ER, PR, HER2, and androgen receptor negative) subtypes of invasive ductal carcinoma patient tumours." (PMID 36622366, 2023).
ischemic disease (1 paper, 2012). Lack of blood supply to an area of the body, resulting in impairment of tissue oxygenation. "HSF1 is expected to be a new therapeutic target for the treatment of ischemic diseases." (PMID 22655083, 2012).
kidney infections (1 paper, 2011). "Our first step towards addressing this major question was to test whether the Hsf1-HSE regulon is expressed during systemic kidney infections by qRT-PCR." (PMID 20817114, 2011). "Secondly, the Hsf1-HSE regulon is activated during systemic kidney infections." (PMID 20817114, 2011).
latent infection (1 paper, 2023). "We observed a significantly greater increase of HSF1 in SHIV-Exo than CTL-Exo, possibly indicating the positive regulation of latent infection in SHIV-infected RM." (PMID 36992502, 2023).
limb ischemia (1 paper, 2012). A ischemia that involves the limb. "We investigated the change in the expression of HSF1 protein in limb tissues and BM cells in WT mice after limb ischemia." (PMID 22655083, 2012). "Moreover, HSF1 expression was also significantly increased in the BM cells from mice with the induction of limb ischemia when compared to the BM cells from healthy mice (P<0.05)." (PMID 22655083, 2012).
malaria (1 paper, 2013). Malaria is a serious and sometimes fatal disease caused by a parasite that commonly infects a certain type of mosquito which feeds on humans. "In particular, the anti-malaria drug quinacrine (QC) was showed to prevent heat shock response in cancer cells and suppresses HSF1 induced HSP70 expression in a relatively selective manner." (PMID 23615731, 2013).
metastatic cancers (1 paper, 2025). A carcinoma which has spread from the original site of growth to another anatomic site. "Our study highlights the important role of DBC1 in HSF1-mediated PCa progression and provides insights into regulatory mechanisms underlying HSF1 stabilization and activation in advanced and metastatic cancers." (PMID 41028522, 2025). "Thus, deciphering mechanisms underlying HSF1 stabilization and activation will provide useful information for developing novel therapeutic approaches for the treatment of a broad range of metastatic cancers and allow significant progress in our understanding of metastatic cancer biology." (PMID 41028522, 2025). "HSF1 protein and phosphorylation levels, genome-wide HSF1 occupancy and HSF1 target gene expression were greatly increased in mCRPC cells, suggesting that HSF1 is hyperactivated and drives a unique transcriptional program in metastatic cancer." (PMID 41028522, 2025).
neuropathy (1 paper, 2021). A disorder affecting the nervous system that manifests with pain, tingling, numbness, and/or muscle weakness. "Direct inhibition of polyQ aggregation by lefunomide or teriflunomide or by indirectly activating HSF1-mediated heat shock response improves PolyQ-induced neuropathy." (PMID 34126963, 2021).
non-Hodgkin lymphoma (1 paper, 2021). Distinct from Hodgkin lymphoma both morphologically and biologically, non-Hodgkin lymphoma (NHL) is characterized by the absence of Reed-Sternberg cells, can occur at any age, and usually presents as a localized or generalized lymphadenopathy associated with fever and weight loss. "Considering the role played by ibrutinib in the management of different non-Hodgkin Lymphomas (i.e., MZL, MCL, DLBCL, WM), HSP70/HSF1 axis inhibition would be of clinical relevance not only in CLL, but also in other B-lymphoproliferative diseases." (PMID 34771616, 2021).
parasitic infections (1 paper, 2025). "The findings of this study support the potential of Hsf1, phytol, and FAME as therapeutic agents against parasitic infections." (PMID 40227390, 2025).
Portal vein thrombosis (1 paper, 2014). Thrombosis of the portal vein and/or its tributaries, which include the splenic vein and the superior and inferior mesenteric veins. "However, the expression of HSF1 was not correlated to HCC patient age, gender, HBV infection status, AFP expression levels, Ceacam1 expression levels and portal vein thrombosis." (PMID 25199534, 2014).
prion disease (1 paper, 2014). A transmissible disease that is caused by a protein that is able to induce abnormal folding of normal cellular proteins, leading to characteristic spongiform brain changes, which are associated with neuronal loss without an inflammatory response. "Therefore, we have identified a new target for the therapeutic treatment of prion diseases – HSF1 – and a combination of drugs with a potent stimulatory effect on the HSF1 transcriptional target Hsp70." (PMID 24523910, 2014). "Moreover, HSF1 knockout accelerates the progression of prion disease in mice, further supporting its protective role against pathogenic PrP." (PMID 24523910, 2014).
progeria (1 paper, 2022). "As part of running controls for other experiments, we found that hsf-1(RNAi) produced a particularly clear progeria phenotype, consistent with its shortened lifespan and accelerated tissue damage." (PMID 36105851, 2022). "Within the Observatory, reducing the function of known lifespan genes with RNA interference (RNAi) gives the expected phenotypic changes, including extended motility in daf-2(RNAi) and progeria in hsf-1(RNAi)." (PMID 36105851, 2022).
retinal diseases (1 paper, 2019). "Considering that numerous small molecules that can activate HSF1 are available, pharmacologically boosting HSF1 activity could be beneficial in a variety of retinal diseases." (PMID 30884523, 2019).
retinal ischemia (1 paper, 2019). A ischemic disease that involves the retina. "Although mechanisms by which HSF1 protects RGCs after retinal ischemia remain to be further investigated, our current study suggests that multiple mechanisms are involved in this process." (PMID 30884523, 2019). "Using a transgenic mouse carrying full-length human HSF gene, we demonstrated that boosting HSF1 expression induces Hsp70 expression, prevents endoplasmic reticulum (ER) stress, abrogates tau phosphorylation and inflammation, and ultimately promotes neuronal survival after retinal ischemia." (PMID 30884523, 2019).
retinoblastoma (1 paper, 2014). A malignant tumor that originates in the nuclear layer of the retina. "Interestingly, differential activation of HSF-1 targets in response to heat stress has been demonstrated in certain cell types; for example, human retinoblastoma cells fail to upregulate Hsp70 upon heat shock, even though HSF-1 is activated and Hsp90 is induced." (PMID 24314125, 2014).
small cell lung carcinoma (1 paper, 2021). Small cell lung cancer (SCLC) is a highly aggressive malignant neoplasm, accounting for 10-15% of lung cancer cases, characterized byrapid growth, and early metastasis. "We have been able to show that a simultaneous knockdown of HSF1, which reduces the expression of Hsp70 and Hsp27, and an inhibition of Hsp90 by AUY-NVP922 improves the radiosensitivity in human H1339 small cell lung cancer cells in vitro." (PMID 34359663, 2021).
sterility (1 paper, 2024). "While in the wild-type animals, loss of HSF-1 from the germline through larval development results in sterility, reduced IIS could partially restore fecundity in the absence of HSF-1 in germ cells." (PMID 39284915, 2024).
systemic candidiasis (1 paper, 2012). "We have shown previously that mutations that block Hsf1 activation attenuate the virulence of C. albicans in a mouse model of systemic candidiasis." (PMID 22448221, 2012).
T-cell leukemia (1 paper, 2024). A malignant disease of the T-lymphocytes in the bone marrow, thymus, and/or blood. "Besides, inhibiting HSF1 with KRIBB11 disrupts these pathways, reduces MDM2 and other survival proteins, induces apoptosis, and enhances sensitivity to HSP90 inhibitors, making HSF1 a promising target to overcome DNA damage repair-mediated chemoresistance in adult T-cell leukemia." (PMID 39850800, 2024).
type 1 diabetic (1 paper, 2017). "FAM3C overexpression increased the protein levels of HSF1, CaM and phosphorylated Akt (pAkt) with the reduced PEPCK and G6Pase protein levels in type 1 diabetic mouse livers." (PMID 29285313, 2017).
vitiligo (1 paper, 2022). Generalized well circumscribed patches of leukoderma that are generally distributed over symmetric body locations and is due to autoimmune destruction of melanocytes. "In response to oxidative stress, vitiligo melanocytes also display a reduced gene expression of ATG5 and ATG12, whose lower levels are caused by a deficiency in the expression of their transcription factor HSF-1." (PMID 36230960, 2022).
cancer (378 papers, 2007 to 2026). A tumor composed of atypical neoplastic, often pleomorphic cells that invade other tissues. "For example, a previous pan-cancer analysis found that HSF1 expression was significantly upregulated in various common cancers and that this upregulated expression was associated with poorer cancer prognosis." (PMID 40699864, 2025). "In summary, we revealed that HSF1 is ubiquitously induced in human iCCA lesions, and HSF1 suppression is detrimental to the growth of malignant cholangiocytes and cancer-associated fibroblasts." (PMID 39243039, 2024). "HSF1 overexpression inhibited mitotic exit, causing an increase in aneuploidy and multinucleated cells, a hallmark of cancer." (PMID 39433125, 2024). "First, it was found that cancer-associated fibroblasts (CAFs) exhibit increased HSF1 activity, which stimulates a program that promotes pro-tumorigenic stroma and tumor progression." (PMID 39682216, 2024). "The pan-cancer analysis of HSF1 reveals that HSF1 is involved in diverse cancer-associated signaling pathways, and is closely associated with immune cell infiltration and efficacy of immunotherapy." (PMID 39261452, 2024). "Manipulating PTMs of HSF1 can inhibit cancer cell proliferation and susceptibility to chemotherapeutics." (PMID 39433125, 2024). "In cultured cancer cells, HSF1 regulates genes associated with proliferation, protein synthesis, and glucose metabolism, thereby facilitating malignant transformation and impacting various cellular functions." (PMID 39248163, 2024). "Mounting evidence indicates that HSF1 positively influences the tumor microenvironment by favoring the growth of cancer-associated fibroblasts (CAFs)." (PMID 39243039, 2024). "Various cancer cells exhibit increased levels of HSF1, and this upregulation is linked to resistance against chemotherapy." (PMID 37958341, 2023). "Later studies revealed that erastin-induced ferroptosis in cancer cells was associated with an elevated HSPB1 expression in an HSF1-dependent manner." (PMID 36976734, 2023). "When HSF1 is deficient, the level of ERα decreases, weakening the cancer cell’s response to E2 and reducing cell motility and adhesion." (PMID 37958341, 2023). "She presented data demonstrating that HSF1 mediates the transcriptional program of cancer-associated fibroblasts (CAFs) resulting in the remodeling of the extracellular matrix and the content of exosomes." (PMID 36602710, 2023). "Due to the diverse malignant manifestations associated with HSF1 in different cancers, we comprehensively review its functions across various cancer types." (PMID 37958341, 2023). "HSF-1 has been reported to facilitate intercellular communication between cancer-associated fibroblasts that is required to promote cancer cell growth." (PMID 36780563, 2023). "NF1-deficient cells become tolerant to proteotoxic stress and, in animal models, HSF1 loss of function contrasts the development of NF1-related cancers by weakening oncogenic Ras/MAPK signaling." (PMID 37627552, 2023). "HSF1 activation is induced in pancreatic stellate cells due to stress imposed on the TME mediated by BRCA-mutated cancer cells." (PMID 37153737, 2023). "Similar to Clu, the induction of Pdl1 was inhibited by aglaroxin C, suggesting an increased immune-regulatory function for PSCs induced by BRCA-deficient cancer cells, in an HSF1-dependent manner." (PMID 36316305, 2022). "Extraordinarily, a significant positive correlation was both observed in COAD and READ between HSF1 expression and the abundance of cancer-associated fibroblast (CAF)." (PMID 35006040, 2022). "HSF1 is infrequently mutated across cancer types, but copy number alterations, especially amplifications, are common." (PMID 35311075, 2022). "In fact, activation of HSF-1 is a common feature of numerous cancer types, and its expression is associated with malignancy and mortality." (PMID 36009046, 2022).
cancer (continued). "Together, these findings suggest that BRCA-deficient cancer cells induce an HSF1-dependent transcriptional program in PSCs." (PMID 36316305, 2022). "We summarized the CNV rate and gene expression rate of HSF1 in CRC through Catalog of Somatic Mutation in Cancer (COSMIC) database analysis." (PMID 35006040, 2022). "The over-expression of heat shock proteins caused by HSF1 is reported as the main cause of resistance to chemotherapy, radiation therapy, and hypothermia used in cancer treatment." (PMID 35268755, 2022). "The 8q21-24 region homes overexpressed oncogenes, such as MYC, heat shock factor 1 (HSF1), and associated cancer signatures." (PMID 36497066, 2022). "Taken together these findings further support the notion that BRCA mutations in the cancer cells lead to a stromal shift from TGFβ induced SMA+ myofibroblasts to HSF1-induced CLU+ fibroblasts." (PMID 36316305, 2022). "The loss of functional active Hsp90 multichaperone complexes in cancer cells elicit an HSF1-dependent anti-stress response, which confers cell resistance and offsets the cytocidal effects of Hsp90 inhibitors." (PMID 36012578, 2022). "Herein, we performed a functional genomics study to analyze comprehensively the consequences of the HSF1 deficiency on the signaling pathways induced by heat shock in cancer cells." (PMID 36010586, 2022). "Using cancer organoids, co-cultures, and in-vivo models we show that loss of BRCA function in cancer cells leads to a transcriptional shift of PSCs from myofibroblastic to immune-regulatory Clu+ CAFs in an HSF1-dependent manner." (PMID 36316305, 2022). "A growing number of studies support that HSF1 is implicated in the initiation, promotion, and progression of cancer and is widely exploited as a potential therapeutic target in a broad spectrum of malignancies." (PMID 36077156, 2022). "And HSF1 expression was positively correlated with cancer associated fibroblast (CAF), myeloid derived suppressor cells (MDSC) and macrophage in COAD." (PMID 35006040, 2022). "Studies in a broad spectrum of cancers showed that active HSF1 is located in the cell nucleus and is associated with poor prognosis." (PMID 35928554, 2022). "Increased HSF1 gene copy number was associated with significantly shorter survival in our pan-cancer analysis." (PMID 35311075, 2022). "We estimated the association between the HSF1 expression and the prognosis of patients in the pan-cancer dataset." (PMID 34239690, 2021). "It was proposed that overexpression of HSF1 in ER-positive breast cancers was associated with a decreased dependency on the ERα-controlled transcriptional program for cancer growth." (PMID 34783649, 2021). "The HSF1 expression was significantly associated with immune infiltration and immune checkpoint markers in various types of cancer." (PMID 34239690, 2021). "The results from Kaplan–Meier analysis suggested that the increased HSF1 expression was associated with a poor prognosis in four types of cancer, namely, ACC, HNSC, PRAD, and UCS." (PMID 34239690, 2021). "Because of the distinct relationship between HSF1 and the immune response, we performed a pan-cancer analysis of the association between the HSF1 expression and the immune infiltration level based on the TIMER database." (PMID 34239690, 2021). "GSEA was performed to examine HSF1-associated signaling pathways that were differentially activated in cancer." (PMID 34239690, 2021). "Th1 and Th2 CD4+ T cells were most positively associated with the HSF1 expression in these different cancers." (PMID 34239690, 2021). "The transcription factor HSF1 is the master regulator of proteotoxic stress responses and supports oncogenesis by helping cancer cells cope with the proteotoxic stress associated with both aneuploidy and oncogenic mutations." (PMID 33376136, 2021). "In several tumors, HSP70 and HSF1 overexpression is one of the causes of low therapy response, allowing cancer cells to escape apoptosis and survive despite stressing conditions." (PMID 34771616, 2021).